MYC (MYC proto-oncogene, bHLH transcription factor)
Diseases named in the same sentence as MYC in open-access papers (continued):
Sharing a sentence is not in itself a finding about the gene and the disease.
lymphoma (continued). "One case was indeterminate due to the morphologic differential diagnosis of high-grade B-cell lymphoma-MYC/BCL2 versus follicular lymphoma with MYC and BCL2 rearrangements, which is not regarded as equivalent to “double-hit” lymphoma according to WHO5/ICC." (PMID 38903717, 2024). "“Quadruple-hit” lymphomas, while not a defined entity in either the WHO or ICC classification schema, have been characterized by the concurrent presence of MYC, BCL2, BCL6, and CCND1 rearrangements, and are extremely rare with an apparent dismal prognosis." (PMID 38914869, 2024). "DLBCL carrying genetic rearrangements of both MYC and BCL-2 genes, with or without a rearranged BCL-6 gene, were formerly known as double-hit (or triple-hit if BCL-6 is also involved) lymphomas." (PMID 37927464, 2023). "Since our case had no rearrangement of MYC or BCL2, it was not consistent with “double-hit” lymphoma." (PMID 37884941, 2023). "In our cohort of 108 cases with the clinicopathological features of BL, which accounted for approximately 1% (108/11,000) of all FNAB/FCM diagnosed lymphomas, we found 12 cases without MYCR as confirmed by CC and FISH with the MYC BAP probe." (PMID 35167621, 2022). "Lymphoma cells expressing CD5 (CD5+) confer inferior outcome of diffuse large B-cell lymphoma (DLBCL), especially in non–MYC/BCL2 double expressor (non-DE) patients." (PMID 36276140, 2022). "The lymphoma cells were positive for CD20, BCL‐6, MUM1, MYC and BCL2, and were negative for CD3, CD5 and CD10, diagnostic of DLBCL, non‐GCB type." (PMID 36467806, 2022). "Currently, aggressive B-cell lymphomas with a combined MYC- and BCL2 and/or BCL6 translocations (so-called double-hit or triple-hit, DH/TH lymphomas) are classified as a separate entity, irrespective of morphological features." (PMID 34099699, 2021). "Lymphoma cells were positive for CD20, CD10, Bcl‐2, Bcl‐6, cyclinD1, Ki67, c‐MYC and negative for CD30, CD5 and MUM‐1." (PMID 34698437, 2021). "DLBCL tumors that co-express both MYC and BCL2 proteins (regardless of genetic rearrangement) are referred to as double expressor lymphomas." (PMID 34282799, 2021). "Expression of MYC and BCL2 proteins is identified by immunohistochemistry (IHC) in some patients with DLBCL even when the chromosomal rearrangements of DH/TH lymphoma are not present." (PMID 34282799, 2021). "However, MYC translocations may occur even in other types of lymphoma and are not specific of BL." (PMID 34572754, 2021). "Consistent with our previous findings, we see that silvestrol blocks the translation of the MYC and BCL2 mRNAs, without affecting the GAPDH housekeeping gene, across several lymphoma lines (SuDHL-4, SuDHL-6, SuDHL-10, Ly8)." (PMID 33562682, 2021). "The prognosis for patients with r/r double-hit lymphoma (concurrent BCL2 and MYC translocations) is extremely poor without active salvage agents." (PMID 33317571, 2020). "The double-expresser lymphomas have a worse outcome than other DLBCLs but they are not as aggressive as the HGBL, with rearrangements of MYC and BCL-2 and/or BCL-6." (PMID 31288832, 2019). "The concomitant double expression of MYC and BCL2 is present in 20% to 30% of DLBCL; the group of DLBCL with these characteristics is termed double expressor lymphomas (DEL), but it is not a different biological entity." (PMID 31942539, 2019). "BCL-2/MYC DE was significantly more common among patients with BCL-2 translocation, as 10 out of a total of 15 BCL-2 -translocated lymphomas had DE and 24 out of a total of 111 without BCL-2 translocation were DE (p = 0.001)." (PMID 30287880, 2018).
lymphoma (continued). "However, ricolinostat did not cause downregulation of cyclin D1 in lymphoma cell lines, and it remains to be determined whether ricolinostat or other HDAC6 selective inhibitors being developed are effective at downregulating MYC and FGFR3 or other FGFRs." (PMID 29423038, 2018). "One of the major limitations in understanding the pathogenesis of MYC/BCL6 DHL is the lack of in vitro and in vivo models by which unlimited supplies of lymphoma cells with concurrent MYC and BCL6 rearrangements can be studied repeatedly and extensively." (PMID 30323893, 2018). "The expression of c-MYC and BCL2 in the “double-expressor” lymphomas is independent of c-MYC or BCL2 gene rearrangement, and is only used as a prognostic marker rather than diagnostic criteria." (PMID 28379189, 2017). "Of note, only 8% of cases harbored a MYC rearrangement and no cases of MYC/BCL2 or MYC/BCL6 double-hit lymphoma were identified." (PMID 28212447, 2017). "These 40 cases are a pure group of MYC/BCL2 DHL, in other words no other DHL or triple hit lymphoma cases, and most patients received immunochemotherapy." (PMID 27203548, 2016). "In these lymphoma lines, it thus seems that JQ1 treatment regulates CYCLON indirectly through MYC rather than through BRD4 – or indeed through BRD2 and 3 which JQ1 can also inhibits." (PMID 23828858, 2013). "To our surprise, we did not observe any difference in lymphoma growth after immunization with full-length c-MYC protein and subsequent challenge with 291 PC cells, even though we observed c-MYC-reactive CD4+ and CD8+ T-cells ex vivo." (PMID 24130880, 2013). "Such cases of "double-hit" leukemia/lymphoma with both BCL2 and MYC translocations warrant further study as they are often not identified early, are associated with a poor prognosis, and are incompletely understood in molecular terms." (PMID 23985173, 2013). "We also identified Rituximab-resistant, lymphoma B cells that overexpress CYCLON, without concomitant MYC deregulation, thus pointing to the existence of other as yet un-identified routes to CYCLON overexpression in lymphoma." (PMID 23828858, 2013). "Closer inspection of GSEA signatures across both conditions revealed, as expected, predominant down-regulation of MYC signatures/target genes, including CYCLON itself, in JQ1-treated but not CYCLON knockdown lymphoma B cells." (PMID 23828858, 2013). "The moderate Ki-67 (60%) and scattered c-Myc positivity indicate a somewhat aggressive clinical course, but the absence of strong MYC positivity and CD5 negativity may suggest a more favorable prognosis than double-hit or highly proliferative lymphomas." (PMID 40062071, 2025). "Indeed, 10% of DLBCL, 90% of Burkitt lymphomas (BL), 100% of double/triple-hit lymphomas, and 45% of high-grade B-cell lymphoma not otherwise specified (HGBL NOS) carry a MYC rearrangement." (PMID 39125743, 2024). "There are rare cases where the translocation of MYC and BCL6 is present in the absence of BCL2 involvement (also defined as DH) and equally rare cases where all three translocations are present, a condition defined as “TH lymphomas”." (PMID 38534887, 2024). "However, only a few, small single institutional studies have described FISH (such as MYC) in FNAB smears and cell block for lymphoma and no comparisons to core biopsy or the gold standard excisional biopsy exist to our knowledge." (PMID 38903717, 2024). "The lymphoma was characterized by a cell-of-origin subtype of germinal center B-cell-like (GCB) based on Hans' classifier (CD10-negative, BCL6-positive, and MUM1-negative); EBER negativity, and the absence of BCL2, BCL6, and MYC rearrangements." (PMID 36975733, 2023).
lymphoma (continued). "Currently, HGBL is subgrouped as HGBL with MYC and Bcl-2 and/or Bcl-6 rearrangements, so-called double- or triple-hit lymphoma (HGBL-DH or HGBL-TH, respectively) and as HGBL, not otherwise specified (HGBL-NOS), which lacks MYC and Bcl-2 and/or Bcl-6 rearrangements." (PMID 35686130, 2022). "In conclusion, although MYC, MYB and ZDHHC11 all have important roles in the growth of HL and DLBCL, the network, as defined in BL with a critical role of miR-150, is not broadly applicable to other GC B-cell derived lymphoma subtypes." (PMID 35205272, 2022). "Lymphomas that co-express the MYC and BCL2 proteins, known as double-expressor lymphomas, are relatively frequent, and have a worse prognosis than other DLBCL-NOS, although their behavior is not as aggressive as that of the DH/TH lymphomas." (PMID 34207773, 2021). "In addition, although MYC, BCL2 and BCL6 rearrangements are important prognostic markers for patients with DLBCL, the sensitivity of lymphoma cell lines to DZNep-mediated apoptosis is independent of these rearrangements." (PMID 31419226, 2019). "In addition, patients with MYC and BCL2 protein co-expression who did not harbour genetic alterations were defined as having “double-expressor” lymphoma (DEL), which accounted for approximately 19–34% of cases of DLBCL." (PMID 31315646, 2019). "They include diffuse large B cell lymphoma (DLBCL), follicular lymphoma (FL), Burkitt’s lymphoma, mixed FL/DLBCL lymphomas, primary mediastinal large B cell lymphoma, multiple myeloma, IRF4-rearranged large cell lymphoma, MYC-negative Burkitt-like lymphoma with chr." (PMID 31039827, 2019). "Because a satisfactory screening for rare cases of MYC/BCL6 DHL has not been defined so far, these flow cytometric findings might be helpful in triaging lymphomas for confirmatory targeted FISH analysis." (PMID 30323893, 2018). "By activating MYC to drive cell proliferation and counteracting MYC-triggered apoptosis by silencing BCL2L11, EBV TFs are manipulating the same pathways that are deregulated in non-viral lymphomas." (PMID 27490482, 2016). "The WHO-HAEM4 provisional entity “Burkitt-like lymphoma with 11q aberration” was named as such because of its clinical, morphological (“starry sky pattern”) and immunophenotypic (CD10+/BCL6+/BCL2−/Ki67 high) resemblance to Burkitt lymphoma but lack of MYC rearrangement." (PMID 36460764, 2023). "For relative comparison, MYC does not rank in the top DEGs of this study, but the extent of downregulation (−17.108-fold change) is greater than the novel DEGs identified further strengthening the utility of selective CDK9 inhibitors for targeting MYC+ lymphomas." (PMID 37882668, 2023). "Additional studies have found that there were 11q aberrations in MYC-negative cases; therefore, the 2016 revision of WHO Classification of Tumours of Haematopoietic and Lymphoid Tissues proposed a new temporary type of lymphoma-Burkitt-like lymphoma with the 11q aberration." (PMID 31484540, 2019). "This study demonstrates that, apparently, there is no distinctive feature of DHL/THL lymphoma with respect to sensitivity to BET inhibitors, and MYC-expressing lymphoma cells are probably addicted to the MYC-oncogenic effect and rely on MYC for their growth regardless of MYC rearrangements." (PMID 31288832, 2019). "The two lymphomas also showed peculiar features: PCTCL are rarely described in HIV+ setting and particularly at such a low clinical stage, and the DLBCL showed uncommon cytology, non-GCB phenotype, EBER negativity, and absence of c-MYC translocation, all atypical features in this clinical context." (PMID 31662919, 2019). "While our findings contrast with a study demonstrating that targeting c-MYC by shRNA or JQ1 treatment decreases PD-L1 in melanoma and lung cancer cells, our findings are in agreement with another study showing that JQ1 regulation of PD-L1 in lymphoma cells is not mediated by c-MYC15." (PMID 30185888, 2018).
prostate carcinoma (771 papers, 2004 to 2026). A carcinoma that arises from epithelial cells of the prostate gland. "Several have been experimentally linked to MYC regulation in cancers, including prostate cancer, B-cell malignancies, and colorectal cancer." (PMID 41251144, 2026). "In contrast, high-dose androgens facilitate the formation of AR dimers/oligomers to suppress c-MYC expression, inhibit proliferation, and drive a transcriptional program associated with a differentiated phenotype of AR-positive prostate cancer cell lines." (PMID 40150035, 2025). "According to preclinical experiments, treatment of MRT‐2359 sensitive prostate cancer cell lines in vitro led to a loss of c‐MYC and, to a lesser extent, AR (including AR‐V7) proteins." (PMID 41194439, 2025). "Considering those pathways beyond the UPR, RNA-seq analyses demonstrated that treatment with NXP800 impacted other key pathways, including AR, MYC, and E2F activity, implicated in prostate cancer treatment resistance." (PMID 39787247, 2025). "In preclinical exploration of MRT‐2359, researchers found that treatment of MRT‐2359 sensitive prostate cancer cell lines in vitro led to a loss of c‐MYC and, to a lesser extent, AR (including AR‐V7) proteins." (PMID 41194439, 2025). "MYC overexpression has previously been associated with radioresistance in prostate cancer and other solid tumors." (PMID 39912912, 2025). "Cluster 4 comprised hallmark pathways associated with cell proliferation (G2M checkpoint, E2F targets, MYC targets), DNA repair and tumor suppressor loss, and the MetB signature associated with a low AR/high proliferation prostate cancer phenotype." (PMID 39985777, 2025). "MYC is strongly linked to the progression of prostate cancer through its overexpression and activation, and it has been reported that these pathways cooperate with others to further promote malignancy." (PMID 40716035, 2025). "The Erythroblast Transformation Specific (ETS) and MYC families are prominent gene families associated with prostate cancer development." (PMID 39410867, 2024). "In this study, we show that miR-377 transfection causes a stop in the cell cycle of prostate cancer cell lines due to the decrease in the expression level of MYC mRNA and, thus, the reduction in the expression level of CDK4 mRNA." (PMID 38756697, 2024). "Numerous investigations have demonstrated that MYC is overexpressed in various types of cancer, including prostate cancer, and is closely associated with tumor advancement." (PMID 38756697, 2024). "Loss of PTEN, higher expression of Ki67 and overexpression of MYC in high-risk prostate cancer prostatectomy specimens have been associated with worse progression-free survival." (PMID 38706600, 2024). "There was also a decrease in nuclear DNA (nDNA) signals after MYC inhibition, which is expected since loss of MYC will also block nDNA synthesis in prostate cancer cells." (PMID 37971875, 2023). "The resultant synergistic effects of MYC/E2F1/TERT expression with the rs2853669 polymorphism further deteriorated the prognosis of prostate cancer." (PMID 37174115, 2023). "The EPIN of CASC11 promoter is also affected by variant rs10090154, the same well known variant associated with risk of developing prostate carcinoma that we introduced with MYC EPIN42,43." (PMID 38057321, 2023). "Aberrant MYC DNA methylations in multiple myeloma, prostate cancer, and colon cancer are associated with more aggressive cancer progression and metastasis." (PMID 34894177, 2022). "Another major driver of prostate tumorigenesis and progression, MYC expression correlates with increased disease severity and it is frequently mutated in prostate cancer, making MYC an intensely researched therapeutic target." (PMID 35406480, 2022). "A risk locus at chromosome 8q24 mapping MYC oncogene is significantly associated with prostate cancer cases with a West African ancestry." (PMID 35912174, 2022).
prostate carcinoma (continued). "By comparing both transcriptomic and proteomic data, three prominent pathways associated with Hsp90 and prostate cancer were identified, namely MYC targets, E2F targets and androgen response." (PMID 35406480, 2022). "The activities of MYC, the androgen receptor, and its associated pioneer factors demonstrate substantial reprogramming between early and advanced prostate cancer." (PMID 36181613, 2022). "The CASC8 gene is responsible for expressing a lncRNA (long non-coding RNA) that plays an important role in the regulation of MYC, which is related to susceptibility to various cancers, such as breast, colorectal, and prostate cancers." (PMID 35741800, 2022). "We determine that an active MYC transcriptional program and low AR activity identify prostate cancer patients predisposed to fail standard-of-care therapies and most likely to develop metastatic castration resistant prostate cancer (mCRPC)." (PMID 35562350, 2022). "Future studies will prospectively evaluate the clinical utility of joint MYC/PTEN status assessment in the setting of intermediate-risk prostate cancer." (PMID 34062284, 2021). "In prostate cancer Akt1 overexpression is associated with accumulation of glycolytic metabolites, whereas overexpression of MYC causes dysregulation in lipid metabolism." (PMID 33652667, 2021). "In pancreatic and prostate cancer, a correlation of MYC with LDHA expression was detected and linked to the regulation of aerobic glycolysis while promoting tumor progression and decreasing apoptosis." (PMID 33925297, 2021). "Activation of MYC is one of the most frequent genetic events linked to the promotion of androgen-independent growth of prostate cancer cells." (PMID 32630240, 2020). "It was previously shown that MYC overexpression and loss of Glipr1 expression co-operate to promote prostate cancer development in vivo." (PMID 31995627, 2020). "Given that enforced GLIPR1 expression in prostate cancer cells caused a reduction in MYC mRNA levels, the effect of Glipr1 re-expression on the expression levels of Myc in 5TGM1 cells was assessed." (PMID 31995627, 2020). "The panel generated from this approach identified as top candidates mutations in known driver genes (e.g. HRAS) and prostate cancer related transcription factor binding sites (e.g. MYC, AR)." (PMID 32859160, 2020). "In localized prostate cancers, up-regulated MYC has been further associated with alterations in nucleoli structure, concomitant with increased biogenesis of ribosomal RNA, increased purine metabolism, and expression of the telomere RNA subunit TERC." (PMID 32681068, 2020). "Taken together, these findings suggest that deregulation of the MYC/E2F1/RB1 cell-cycle regulator axis by various means is a ubiquitous event in AR indifferent prostate cancer that is necessary to overcome the G1 arrest caused by low AR activity." (PMID 31551480, 2019). "Region surrounding rs378854 which is identified as a novel function prostate cancer-specific genetic variant interacts with the MYC and PVT1 promoters." (PMID 31760932, 2019). "For example, loss of ZFHX3 dramatically increased MYC expression in both C4-2B and LNCaP prostate cancer cells, and ZFHX3 clearly bound to the MYC promoter." (PMID 30979864, 2019). "Saturated fat intake (SFI) is also associated with an enhanced MYC transcriptional signature in prostate cancer patients." (PMID 31554818, 2019). "This has been demonstrated recently in prostate cancer, where certain mtDNA mutations that co-occur with the MYC oncogene jointly associate with patient survival." (PMID 31323957, 2019).